ALB (albumin)
Diseases named in the same sentence as ALB in open-access papers (continued):
Sharing a sentence is not in itself a finding about the gene and the disease.
malnutrition (continued). "These nutritional status indices have never been used to assess the risk of tumor incidence, but the three indices all include serum albumin levels in the calculation of nutritional status, which can indicate malnutrition status, especially in patients after surgery and undergoing chemotherapy." (PMID 37836494, 2023). "Moreover, two prospective cohorts, in which a decrease in BMI and lower hemoglobin and albumin levels, which are indicators of malnutrition, were detected during the course of DLB, partially supported our study." (PMID 36945932, 2023). "Albumin levels may be reduced by varying degrees due to malnutrition, such as advanced cachexia, as well as inhibition of inflammatory reactions, resulting in poor prognosis in cancer patients." (PMID 37809958, 2023). "Most importantly, we considered albumin levels, which might be a surrogate marker for chronic disease, malnutrition, or poor health status in our analysis." (PMID 36643628, 2023). "Similarly, non-malnutrition and suspected/moderate to severe malnutrition groups presented that hs-CRP (OR=3.346, 95%CI=1.833-6.122; P< 0.001), age, HB, ALB, BMI and BWL were independent risk factors for malnutrition in GC." (PMID 37293590, 2023). "Although early screening tools may vary greatly due to differences in focus indicators, such as body weight, albumin, inflammation, and immune; malnutrition screening tools is effective to identify people who may have or develop to malnutrition." (PMID 37537542, 2023). "However, it should be noted that the current state of health is a significant factor in the diagnosis of malnutrition using albumin levels." (PMID 37571292, 2023). "In fact, there are reports that MNA scores of 17–23.5 (risk of malnutrition) detected older adult patients with poor nutritional intake and, at the same time, normal albumin levels or no loss of body weight." (PMID 37892494, 2023). "Decreased serum ALB levels have been extensively described in rheumatoid arthritis (RA), mainly due to suppression of hepatic production by inflammatory cytokines storm, hemodilution and malnutrition status." (PMID 37762957, 2023). "Furthermore, IL-6 can have a catabolic effect, promoting muscle wasting and inhibiting albumin synthesis, exacerbating malnutrition in MM patients." (PMID 37512137, 2023). "For example, albumin (Alb) can be a marker of disease severity, but not a malnutrition indicator, whilst low levels of Alb can be associated with an increased mortality rate in hospitalized patients." (PMID 36597167, 2023). "As serum albumin levels are a parameter to determine the sarcopenia status as well as malnutrition, we hypothesize that NMES has a positive effect on serum albumin levels in HD patients and, thus, could impact protein energy wasting and sarcopenia." (PMID 37608265, 2023). "In the case of long-term malnutrition, the concentration of serum albumin decreases." (PMID 37833779, 2023). "Typically, a serum albumin concentration of <3.5 g/dL indicates malnutrition." (PMID 37571292, 2023). "Moreover, systemic inflammation and malnutrition can be captured by serum albumin, and hypoalbuminemia is a renowned predictor of poorer prognoses in cancer." (PMID 35702873, 2023). "A number of international bodies advise against the use of albumin as a marker for malnutrition." (PMID 37749757, 2023). "Mathus–Vliegen reported that a decrease in albumin levels in elderly patients suggested malnutrition, and the presence of accompanying pressure sores could lead to a very poor prognosis." (PMID 36776614, 2023). "Low albumin level is widely used as a predictor of malnutrition." (PMID 37700304, 2023). "Low albumin levels were indicative of malnutrition and inflammation within the body." (PMID 36950094, 2023). "However, low albumin serum concentrations still have a predictive role in adverse outcomes in different clinical contexts of disease-related malnutrition, as demonstrated in recent studies." (PMID 36986202, 2023).
malnutrition (continued). "Serum albumin and plasma hemoglobin are commonly regarded as laboratory parameters reflecting nutritional status, and they are typically measured at lower concentrations in patients with malnutrition." (PMID 38249615, 2023). "Therefore this study aims to evaluate serum albumin, Total Protein (TP), and Hemoglobin (Hgb) and their correlation with malnutrition in patients with cancer at Jimma Medical Center (JMC)." (PMID 36869395, 2023). "Similarly, in the case of malnutrition, several studies highlighted the shortcomings of using only albumin and BMI as markers for malnutrition." (PMID 37568924, 2023). "We aimed to analyze malnutrition status based on total proteins and albumin levels." (PMID 38130551, 2023). "In addition, some studies have supported that malnutrition and inflammation play a major role in low level of serum albumin and the influence of inflammation on serum albumin level seems to be stronger." (PMID 37974066, 2023). "The existence of significant association between higher globulin and higher mortality after adjustment of nutritional indicators, such as BMI, serum albumin, and nPNA, excludes the possibility of globulin-mortality relation caused by malnutrition." (PMID 36670150, 2023). "Although albumin may have a role in prognostication for surgical outcomes, the use of albumin as a marker of the current state of malnutrition should be abandoned, clinically and in future studies." (PMID 37749757, 2023). "The role of serum biomarkers, specifically albumin, in diagnosing or monitoring malnutrition remains controversial due to the lack of associated specificity and longer half-life (approx. 20 days)." (PMID 36694739, 2023). "However, after including serum albumin and hs-CRP concentrations (bioindicators of malnutrition and inflammation) in the analysis, the association of fT3 with mortality disappeared." (PMID 36771302, 2023). "Therefore, this study aims to evaluate serum albumin, TP and Hgb derangements correlated with SGA tool as an alternative diagnostic modality for early and better diagnosis of malnutrition." (PMID 36869395, 2023). "Reduced serum albumin levels could be indicative of malnutrition, liver disease, inflammation, or increased capillary permeability, conditions that are often present in critically ill patients." (PMID 37626427, 2023). "Albumin is a marker of malnutrition widely discussed in the literature." (PMID 37571416, 2023). "Low albumin levels suggest decreased immune response and malnutrition." (PMID 38137581, 2023). "The inflammatory reaction, in turn, could antagonize albumin synthesis, a key protein involved in maintaining optimal nutritional status, and further aggravate malnutrition, engendering a self-perpetuating cycle of deleterious consequences." (PMID 37645626, 2023). "Therefore, the main factors affecting serum albumin are inflammation and malnutrition in these patients." (PMID 37974066, 2023). "According to the serum albumin level, 29.6% had malnutrition criteria." (PMID 36276928, 2022). "Patients with malnutrition had lower serum albumin and creatinine concentrations." (PMID 34590669, 2022). "However, they are not accurate enough to define malnutrition, but in the present study, a decrease in serum albumin and prealbumin were the parameters that most accurately diagnosed malnutrition according to 74.1% of participants." (PMID 36432451, 2022). "Albumin to globulin ratio (A/G) includes serum albumin and globulin, two objective and easily measurable components of human serum proteins commonly employed in clinical practice to reflect and identify inflammation and malnutrition." (PMID 36051899, 2022). "Notably, the malnutrition indicators of erythrocyte, hemoglobin, albumin, and total protein levels were consistently and significantly associated with MMSE, ADL and CDR scores, with all levels of P < 0.001." (PMID 35265656, 2022).
malnutrition (continued). "Albumin is a negative-phase reactant protein, and its association with survival does not reflect malnutrition necessarily." (PMID 35865866, 2022). "Additionally, albumin levels are correlated with nutritional status, with lower albumin levels acting as an important denominator of malnutrition and poor general condition." (PMID 36533070, 2022). "In addition, upon examining obtained laboratory data, only serum albumin presents a high correlation with malnutrition." (PMID 36286208, 2022). "These losses are usually exceeded by the albumin synthesis in the liver, but the rate of synthesis could be suppressed due to inflammation and malnutrition." (PMID 36079811, 2022). "The decline in prealbumin and albumin usually indicates the existence of malnutrition." (PMID 35591765, 2022). "A meta-analysis revealed that pre-albumin concentrations <20 mg/dL may indicate malnutrition, so we chose this value as the cutoff value for the current study." (PMID 36742004, 2022). "However, the personalized nutrition intervention reduced the prevalence of malnutrition in both groups, and the levels of albumin, protein, hemoglobin, and hematocrit were improved in all patients, especially in the obese group (p < 0.05)." (PMID 36078901, 2022). "Therefore, CRP, and thus immune activation, correlates reciprocally with serum albumin levels, which is generally considered a marker of malnutrition and liver function." (PMID 35327399, 2022). "Moreover, among patients with MetS, HbA1c ≥5.7% was also related to higher hemoglobin levels, higher albumin levels, and lower prevalence of malnutrition–inflammation." (PMID 36009406, 2022). "In fact, low albumin levels are indicators of malnutrition, maybe due to long term protein reduction." (PMID 36014924, 2022). "Second, too many factors affect serum albumin levels, such as chronic liver disease, malnutrition, infections, and cancer, which may alter the experimental results." (PMID 35709212, 2022). "The expression levels of serum ALB (31.91 ± 7.52 vs. 35.73 ± 5.72), PA (31.52 ± 9.05 vs. 36.44 ± 6.58) and Hb (91.20 ± 23.90 vs. 98.17 ± 27.69) in the malnutrition group were significantly lower than those in the normal group, and the difference was statistically significant (P < 0.05)." (PMID 36687720, 2022). "In addition, low serum albumin levels as an indicator of malnutrition status in patients have been validated to weaken the anti-tumor defense, leading to poor prognoses." (PMID 35448194, 2022). "However, in severe cases of malnutrition, a decrease in albumin below the normal range can be observed also after bariatric surgeries, which can prompt redo surgeries." (PMID 35807778, 2022). "Therefore, a decreased albumin level reflects malnutrition status and the intensity of the inflammatory response." (PMID 36238862, 2022). "Serum albumin levels during pregnancy might be affected by maternal inflammatory and malnutrition status or protein metabolism." (PMID 36474218, 2022). "In the past, serum albumin was widely used as an indicator of malnutrition in older patients." (PMID 36687683, 2022). "According to the serum albumin level, 29.6% (n = 8) had malnutrition criteria." (PMID 36276928, 2022). "Consideration of an extra parameter, as well as a certain corporation of ALP and albumin, whose lower levels may suggest cachexia and malnutrition, could result in improved accuracy of the model comprising ALP." (PMID 35956107, 2022). "The prevalence of malnutrition using serum albumin concentration was found to be 13.1%." (PMID 36411835, 2022). "According to these guidelines, serum albumin must be recognized as an inflammatory marker associated with “nutrition risk” in the context of nutrition assessment, rather than with malnutrition per se." (PMID 35267906, 2022).
malnutrition (continued). "Compared to those with the presence of other malnutrition risk groups, patients without malnutrition had higher lymphocyte counts, total cholesterol, and albumin and were less likely to undergo anticoagulant therapies before admission." (PMID 36276820, 2022). "Surgeons can utilize this information to either modify risk factors by advising lifestyle changes, e.g. in the case of BMI and albumin (as an indicator of malnutrition), or wherever possible by choosing certain procedural modifications, e.g. in the case of open versus laparoscopic approaches." (PMID 35705550, 2022). "A low level of albumin is commonly regarded as an indicator of malnutrition." (PMID 35922845, 2022). "Serum pre-albumin could be a marker indicating malnutrition and other potential pathological conditions, such as inflammation, in clinical practice." (PMID 35545756, 2022). "Lower serum albumin level is thought to reflect both malnutrition and systemic inflammatory status." (PMID 35413824, 2022). "Inflammation and malnutrition both lead to a depletion of albumin while a low lymphocyte count may represent impaired host immune-surveillance." (PMID 35925991, 2022). "Malnutrition was underlined by the strong negative correlation of BMI with albumin (p = 0.001) and hemoglobin (p = 0.001)." (PMID 36286205, 2022). "Thus, PC can lead to lower ALB levels by inducing malnutrition and anorexia, further leading to disease progression and forming a vicious circle." (PMID 35663321, 2022). "In addition, low ALB concentrations also indicate malnutrition, which can negatively affect tumor immunity in the microenvironment." (PMID 35280794, 2022). "Frailty was assessed with a comprehensive geriatric assessment, which included nine items (presence of malignancy, number of comorbidities, serum albumin level, ADL score, IADL score, presence of dementia, risk of delirium, presence of malnutrition, and midarm circumference)." (PMID 35513758, 2022). "Consequentially, the CRP/albumin ratio (CAR) can reflect inflammation as well as malnutrition." (PMID 36079002, 2022). "In addition, due to malnutrition, anorexia, or abnormal liver function, the albumin levels of patients with advanced disease were reduced." (PMID 36221349, 2022). "Patients may experience a decrease in body weight and lean body mass and a decrease in albumin and prealbumin levels, resulting in malnutrition and even cachexia." (PMID 35910071, 2022). "First, low serum albumin levels are a marker of malnutrition." (PMID 35419326, 2022). "Malnutrition status assessed by both the MNA and serum albumin level could predict 3-month all-cause mortality after discharge with ORs of 3.519 (95% CI: 1.254–9.872, P = 0.017) and 3.848 (95% CI: 1.465–10.105, P = 0.006), respectively." (PMID 36687683, 2022). "Our data showed that ESKD patients with CVC had lower levels of hemoglobin and albumin, and hypoalbuminemia was an independent risk factor for CVC, suggesting that malnutrition might play a role in the development of CVC in ESKD patients." (PMID 35166181, 2022). "Lastly, the method for malnutrition assessment still included albumin which has been recommended not to be used as a diagnostic marker." (PMID 36078901, 2022). "The serum albumin value at diagnosis was used as an index of malnutrition." (PMID 36054114, 2022). "Therefore, serum albumin is used as a highly correlated malnutrition index and a useful index of malnutrition or cachexia in cancer patients." (PMID 35392884, 2022). "However, it still harbors several pitfalls in tumor patients, such as inflammation and malnutrition, that can undoubtedly influence relevant parameters such as albumin as an integral part of those scores." (PMID 36230506, 2022). "Serum albumin, a stable protein synthesized in the liver and has been considered to be a powerful prognostic marker in the general population and many pathological settings, mainly as the result of malnutrition and inflammation." (PMID 36401191, 2022).
malnutrition (continued). "Preoperative malnutrition with low albumin has occurred in 19.1% of PDAC patients." (PMID 36578944, 2022). "BMI, LDL, total cholesterol, albumin, and lymphocytes were significantly higher in the group of patients who were not at risk of malnutrition." (PMID 35627363, 2022). "In addition to risk for malnutrition based on the RMNST, serum albumin and a low MA (< 31 HU) were associated with shorter OS in univariate analysis." (PMID 34734326, 2022). "Albumin is a typical marker that is used to assess malnutrition, but its concentration may not only be affected by protein intake but also by overhydration, inflammation or other factors." (PMID 35627363, 2022). "ALB is recognized as an important marker for long-term malnutrition and systemic stress response." (PMID 36267459, 2022). "Albumin is a multifaced protein synthesized in the hepatocytes that has many physiological properties, including anti-inflammatory, antioxidant, anticoagulant, and anti-platelet aggregation activities, and serum albumin has been assigned as an indicator of malnutrition." (PMID 35328045, 2022). "By comparing the clinical characteristics in each group, the elderly gastric cancer patients with both sarcopenia and malnutrition were found to present the oldest age, lowest BMI, lowest albumin and hemoglobin levels, lowest muscle mass, and poorest muscle function." (PMID 36061885, 2022). "Meanwhile, albumin is a biomarker for malnutrition–inflammation syndrome." (PMID 35297102, 2022). "Low albumin is one of the manifestations of patients with malnutrition." (PMID 35279208, 2022). "This ROC curve analysis was also performed with other nutritional parameters: albumin predicted malnutrition with a value of 0.77 (95% CI: 0.741–0.801) and a cut-off point for predicting the appearance of PEW in this population of 3.71 mg/dL, with lower sensitivity (66%)." (PMID 36014879, 2022). "High dose albumin therapy is also considered to improve patients' behavioral function within the effective treatment time window, suggesting that malnutrition may be a potential target." (PMID 35340417, 2022). "Moreover, BMI and albumin as indicators of nutrition status were also analyzed in PSM, Cox models, and logistics models to control the bias caused by malnutrition." (PMID 36510169, 2022). "Meanwhile, Low albumin level is also the manifestation of the heightened systemic inflammatory reaction and malnutrition, which also may affect the prognosis of osteosarcoma." (PMID 35086516, 2022). "Increase of ALB by QFG might provide a possibility in the improvement of malnutrition and cancer-related fatigue for patients." (PMID 35280511, 2022). "Albumin was considered an important biomarker of malnutrition and inflammation in patients with HF." (PMID 36371183, 2022). "Since the 0.3 and 0.5% ROD extract did not negatively affect liver enzymes, growth parameters, and gut morphology compared to the antibiotic and control treatments, the reduced ALB and increased GLB cannot be associated with malnutrition or chronic inflammation in birds." (PMID 35544959, 2022). "As another important risk factor for calciphylaxis, several researches have discovered that a significant decrease in albumin level in patients with typical malnutrition, which requires strengthening supportive treatment, such as improving nutrition, supplementing albumin and correcting anemia." (PMID 35755071, 2022). "Further studies should be executed with updated assessments for malnutrition excluding albumin." (PMID 36078901, 2022). "Low albumin levels are associated with malnutrition and weight loss, which has a negative impact on the survival and recovery of cancer patients." (PMID 36498630, 2022). "Malnutrition, which might be reflected by low serum albumin levels, can weaken defense, including the anatomic barriers, cellular and humoral immunity, and phagocyte function." (PMID 36313734, 2022).